GATA2 (GATA binding protein 2)
Diseases named in the same sentence as GATA2 in open-access papers (continued):
Sharing a sentence is not in itself a finding about the gene and the disease.
hypothyroidism (5 papers, 2011 to 2022). Abnormally low levels of thyroid hormone. "It was reported that some patients with GATA2 deficiency have not only hematological disorders but also clinical features, such as sensorineural hearing loss, miscarriage, and hypothyroidism." (PMID 34576178, 2021). "Pituitary-specific GATA2 knock-out mice show transient loss of thyrotroph cells and decreased production of TSH in response to hypothyroidism induction, in addition to compromised gonadotroph function." (PMID 36612109, 2022). "We observed robust reduction in GATA2 mRNA expression by T3 at concentrations corresponding to those between mild hypothyroidism and euthyroidism." (PMID 31940421, 2020). "GATA2 mRNA was drastically suppressed by T3, the concentration of which corresponds to moderate hypothyroidism and euthyroidism." (PMID 31940421, 2020). "This is supported by the report that pituitary-specific GATA2-knockout mice exhibit reduced TSHβ expression in hypothyroidism, where stimulation by TRH should be elevated." (PMID 21533184, 2011). "Unfortunately, because information about whether hypothyroidism is primary or central is lacking in the literature, GATA2 mutations may predispose patients to develop primary hypothyroidism caused by Hashimoto’s thyroiditis." (PMID 34576178, 2021). "Although detailed analysis has not been performed, hypothyroidism in patients with mutant GATA2 has been reported." (PMID 31940421, 2020). "Furthermore, a recent study of pituitary-specific GATA2 Knockout mice demonstrated reduced pituitary TSH content and serum TSH levels, and pituitary TSHβ mRNA showed a defective response to hypothyroidism." (PMID 22792320, 2012). "However, while deleting ISL1 in TSH-Cre mice results in a phenotype resembling hypothyroidism, it does not entirely ablate thyrotroph cells, similar to GATA2 knock-out mice." (PMID 36612109, 2022).
lung adenocarcinoma (5 papers, 2017 to 2025). A carcinoma that arises from the lung and is characterized by the presence of malignant glandular epithelial cells. "More importantly, inhibition of GATA2 markedly inhibits the growth of KRAS-driven lung adenocarcinoma." (PMID 40647501, 2025). "In Hou's dataset 31 and Garber's dataset 32, the transcription levels of GATA2 in squamous cell lung carcinoma, lung adenocarcinoma and large cell lung carcinoma were both lower than those in lung tissues, and their FC are -3.780/-2.475/-4.077 and -3.551/-2.318/-2.194, respectively." (PMID 34093794, 2021). "Furthermore, the results from different datasets showed that there were -4.430-fold, -2.451-fold, -2.552-fold, -2.361-fold, -2.218-fold and -3.332-fold decrease in GATA2 mRNA expression in lung adenocarcinoma, respectively 25-29." (PMID 34093794, 2021). "In order to verify the clinical value of the model, we finally examined the expression of FERMT2, FKBP3, SMAD9, GATA2 and ITIH4 in 30 lung adenocarcinoma tissues by immunohistochemistry, considering the availability of antibodies." (PMID 33648465, 2021). "The increased GATA2/3/5/6 mRNA levels and the decreased GATA4 mRNA levels in lung adenocarcinoma were remarkably related to improved OS." (PMID 34093794, 2021). "While GATA2, 3, and 6 bind to the +220 GATA site, GATA3 is highly expressed in lung and lung adenocarcinoma." (PMID 29299165, 2017). "In Bhattacharjee dataset 24, GATA2 has a lower expression than normal samples in four different LC types: SCLC with a fold change (FC) of -13.297, squamous cell lung carcinoma with a FC of -8.029, lung adenocarcinoma with a FC of -6.027, and lung carcinoid tumor with a FC of -12.984." (PMID 34093794, 2021). "In a study on lung adenocarcinoma, four fusion genes (WISP1, RAMP1, MYBL2, and GATA2) of the human leukocyte antigen (HLA) family were identified by RNA-seq technology, indicating that the HLA family genes might be potential targets for the lung adenocarcinoma therapy." (PMID 32117438, 2020).
lymphoma (5 papers, 2016 to 2025). A malignant (clonal) proliferation of B- lymphocytes or T- lymphocytes which involves the lymph nodes, bone marrow and/or extranodal sites. "In addition to the known association between GATA2 mutation and lymphoma, lymphoma can be caused by immunosuppression- associated overwhelming carcinogenic infections like Epstein-Barr Virus (EBV) Infection." (PMID 41438140, 2025). "While lymphoma has been reported in GATA2 deficiency, current data are insufficient to determine whether the relationship is causal or reflects a broader predisposition due to immune dysregulation." (PMID 41438140, 2025). "Although the underlying GATA2 mutation did not directly obscure classic lymphoma manifestations, its presence remains clinically relevant, as GATA2 deficiency is associated with immune dysregulation and susceptibility to recurrent or refractory infections that may complicate clinical assessment." (PMID 41438140, 2025).
pancreatic cancer (5 papers, 2019 to 2025). "Conversely, downregulation of GATA2 markedly reduced the metastatic potential of these cells, highlighting its critical role in pancreatic cancer dissemination." (PMID 41514651, 2025). "For instance, in pancreatic cancer, GATA2 was found to bind to the promoter regions of Notch3 and transcriptionally activate its expression, thereby promoting the metastasis of pancreatic cancer cells to the liver." (PMID 41514651, 2025). "Bmi1, a polycomb group (PcG) protein, was found to be up-regulated by high glucose, and mediated the inhibition of MICA/B expression through promoting GATA2 in pancreatic cancer." (PMID 31088566, 2019). "In order to verify the role of GATA2 on MICA/B gene expression, loss-of-function of GATA2 in pancreatic cancer cells was achieved by siRNA knockdown." (PMID 31088566, 2019). "Notably, this expression pattern of GATA2 contrasts sharply with that of REEP3 in pancreatic cancer." (PMID 38879709, 2024). "We further verified the effect of high glucose on GATA2 expression in pancreatic cancer cells." (PMID 31088566, 2019). "Moreover, Bmi1 inhibits MICA/B expression through up-regulating of GATA2 in pancreatic cancer cells, contributing to the immune escape eventually." (PMID 31088566, 2019). "Next, we investigated whether Bmi1 was involved in regulating GATA2 expression in pancreatic cancer cells." (PMID 31088566, 2019). "Moreover, high glucose inhibited AMP-activated protein kinase signaling, leading to high expression of Bmi1, a polycomb group (PcG) protein which was found to be up-regulated by high glucose, and mediated the inhibition of MICA/B expression through promoting GATA2 in pancreatic cancer." (PMID 32631421, 2020). "Our research may open a new avenue to GATA2 research in pancreatic cancer." (PMID 31088566, 2019). "Research has revealed that high glucose levels can enhance the expression of polycomb protein Bmi1, leading to increased GATA2 levels and suppression of cell surface MICA/B expression, thereby facilitating immune evasion in pancreatic cancer cells." (PMID 38879709, 2024). "We further verified that high glucose can promote the GATA2 to bind to the MICA and MICB promoter in pancreatic cancer under high glucose environment using ChIP assay." (PMID 31088566, 2019). "Furthermore, disparate expression patterns of GATA2 and REEP3 were observed in two GEO datasets, suggesting a potential interaction between GATA2 and REEP3 in the progression of pancreatic cancer." (PMID 38879709, 2024). "Moreover, after AMPK signaling was activated under high glucose, Bmi1 decreased, GATA2 increased and MICA/B recovered in pancreatic cancer cells." (PMID 31088566, 2019). "In this study, we develop our hypothesis that high glucose affects the expression of Bmi1, AMPK, GATA2, and MICA/B and promotes pancreatic cancer cells to escape from immune surveillance." (PMID 31088566, 2019).
Pancytopenia (5 papers, 2016 to 2023). An abnormal reduction in numbers of all blood cell types (red blood cells, white blood cells, and platelets). "GATA2 plays an important role in B-cell and dendritic cell development, and decreased numbers of those cells is a characteristic feature that should prompt consideration of GATA2 deficiency in a patient with pancytopenia." (PMID 29588856, 2018). "This may be a common nature of those critical hematopoiesis regulators including Gata2 gene since both GATA2 deficiency and overexpression impaired HSC function and caused pancytopenia in mice." (PMID 27222706, 2016). "It is not clear whether this germline GATA2 variant contributed to this JAK2 positive myeloproliferative neoplasm and/or if it drove the pancytopenia." (PMID 34387894, 2021).
WHIM syndrome (5 papers, 2016 to 2023). "Cutaneous viral infections are described in CARD11, LCK, NEMO, GATA2, STK4, DOCK8, and STAT2 deficiencies, STAT1 GOF, Netherton syndrome, WHIM syndrome, and WILD (warts, depressed cell‐mediated immunity, primary lymphedema, and anogenital dysplasia) syndrome." (PMID 37102642, 2023).
diabetes (4 papers, 2014 to 2022). "For example, it has been shown that GATA2 plays an important role in diabetes development and associated diseases." (PMID 36451736, 2022).
Hypertension (4 papers, 2019 to 2025). The presence of chronic increased pressure in the systemic arterial system. "Another study reported that GATA2 is an important risk factor for T2D137, dyslipidemia and hypertension (HTN)." (PMID 39160196, 2024). "A variety of statistically significant genetic polymorphisms were identified that can be attributed to the heritability of varicose veins affecting inflammation and immunity (eg, PPP3R1, EBF1, and GATA2), hypertension (eg, CASZ1), and vascular architecture (eg, CASZ1, PIEZO1, and STIM2)." (PMID 41391741, 2025).
hypogammaglobulinemia (4 papers, 2020 to 2024). "The patient with the GATA2 variant in this study also showed similar features, with a history of recurrent infection with mycobacterial infection, hypogammaglobulinemia, and B and NK cell deficiency." (PMID 37325673, 2023). "Patient P10 had agammaglobulinemia phenotype with unknown genetic cause as found by Whole Exome Sequencing while patient P11 was diagnosed with GATA2 deficiency." (PMID 32765500, 2020). "Hypomorphic mutations in other IEI genes (BTK, GATA2, IL2RG, JAK3, RAG1, RAG2, etc.)have been previously found in patients with antibody deficiency and milder phenotypes or in CVID patients." (PMID 34975878, 2021).
melanoma (4 papers, 2021 to 2025). A malignant, usually aggressive tumor composed of atypical, neoplastic melanocytes. "GATA2, a zinc finger transcription factor, plays a role by influencing melanoma biology and lymphatic angiogenesis." (PMID 39624268, 2024). "GATA2, on the other hand, plays a role in immune cell development and function, which could influence the immune response in both PD and melanoma." (PMID 40066251, 2025).
osteosarcoma (4 papers, 2021 to 2025). A usually aggressive malignant bone-forming mesenchymal neoplasm, predominantly affecting adolescents and young adults. "When delivered via serum-derived exosomes, miR-15a is internalized by osteosarcoma (OS) cells, where it directly targets GATA-binding protein 2 (GATA2), inhibiting transcription and binding to the MDM2 promoter." (PMID 41323391, 2025). "Further assays showed that serum-derived exosomes with miR-15a can be internalized by osteosarcoma cells and then miR-15a directly binds to GATA binding protein 2 (GATA2) to inhibit its expression." (PMID 35592419, 2022).
prostate tumor (4 papers, 2016 to 2024). "Importantly, GATA2 overexpression in prostate tumor has been associated with increased motility and invasiveness, proliferation, tumorigenicity, and chemoresistance, whereas in PDAC it was found increased in high-grade tumors and cell lines." (PMID 39114357, 2024). "To assess whether GATA2 genome alterations display any clinical impacts on PCa, we evaluated potential correlation between GATA2 copy number gain and its expression levels in human prostate tumors." (PMID 37550764, 2023). "Pioneer transcription factors, including FOXA1, HOXB13, and GATA2, as well as the transcription factor ERG, have prominent roles to play in earlier, hormone-sensitive stages of the disease and in CRPC where AR signaling remains a mainstay of prostate tumor growth." (PMID 36212399, 2022).
acute promyelocytic leukemia (3 papers, 2022 to 2023). An aggressive form of acute myeloid leukemia (AML), characterized by arrest of leukocyte differentiation at the promyelocyte stage, due to a specific chromosomal translocation t(15;17) in myeloid cells. "GATA2-mediated inhibitory mechanisms in NPmut AML cells are distinct from those in acute promyelocytic leukemia." (PMID 37847561, 2023).
autoimmune conditions (3 papers, 2015 to 2024). "In the B cell compartment, the CD38−CD21− population, previously reported to be associated with autoimmunity, is increased in some GATA2 patients." (PMID 25707267, 2015).
autoimmune disease (3 papers, 2020 to 2024). A disorder resulting from loss of function or tissue destruction of an organ or multiple organs, arising from humoral or cellular immune responses of the individual to their own tissue constituents. "Genes CPA3 and GATA2 expression were positively associated with levels of leptin, suggesting a genetic overlap between AN, autoimmune disease, and metabolic function." (PMID 39462405, 2024). "Through an ongoing National Institutes of Health (NIH) study of GATA2 deficiency, we identified patients with rheumatological findings, specifically patients with definable autoimmune diseases and others with musculoskeletal (MSK) manifestations." (PMID 32433473, 2020). "In this large retrospective study, we have characterized rheumatological manifestations in patients with GATA2 deficiency, specifically identifying musculoskeletal and autoimmune diseases." (PMID 32433473, 2020).
autoimmune hepatitis (3 papers, 2016 to 2022). Hepatitis caused by autoantibodies. "Additionally, mutations in GATA2 have been associated with autoimmune hepatitis." (PMID 36157881, 2022).
B- cell lymphopenia (3 papers, 2015 to 2023). "Interestingly, mutations in GATA2 have been associated with B-cell lymphopenia, which was a prominent characteristic in our patient." (PMID 37959410, 2023).
cryptococcosis (3 papers, 2019 to 2025). An acute or chronic, localized or disseminated infection by Cryptococcus neoformans. "Monogenic mutations, such as those in the zinc transcription factor GATA2 gene, the transcriptional activator STAT3 gene, and the CD40 ligand CD40LG gene, are also associated with cryptococcosis in seronegative HIV patients (39, –, 41)." (PMID 30755511, 2019). "Additionally, rare conditions such as idiopathic CD4 lymphocytopenia and inborn errors of immunity, including GATA2 deficiency, have been reported as potential underlying causes of cryptococcosis in non-HIV patients." (PMID 41458507, 2025).
dementia (3 papers, 2020 to 2022). Loss of intellectual abilities interfering with an individual's social and occupational functions. "Although there is no direct evidence linking GATA2 and ELK1 with ALS, these transcription factors have been associated with dementia and neurodegeneration." (PMID 35370543, 2022).
Endometrium (3 papers, 2016 to 2024). "GATA2 haploinsufficient women affected by HPV should undergo more frequent cervical cancer screening as recommended for these other populations." (PMID 39267745, 2024).
endothelial dysfunction (3 papers, 2017 to 2022). In vascular diseases, endothelial dysfunction is a systemic pathological state of the endothelium (the inner lining of blood vessels) and can be broadly defined as an imbalance between vasodilating and vasoconstricting substances produced by (or acting on) the endothelium. "Together, this data provides evidence that endothelial GATA2 mRNA expression is reduced by inducing endothelial dysfunction, using either media rich in placental factors, or TNFα." (PMID 30659233, 2019). "We next investigated the effects of silencing GATA2 on markers of endothelial dysfunction, VCAM-1 and ET-1." (PMID 30659233, 2019). "As such we wondered if any of these therapeutics might modulate GATA2 mRNA expression, which we found was reduced in endothelial dysfunction." (PMID 30659233, 2019). "We further suggest that the decrease in endothelial dysfunction induced by resveratrol may be via a GATA2 pathway." (PMID 30659233, 2019). "Interestingly, we demonstrated that resveratrol rescued the TNFα-induced down regulation of GATA2 mRNA expression in our model of endothelial dysfunction." (PMID 30659233, 2019). "We next investigated if there was a treatment that could rescue the decrease in GATA2 expression seen with endothelial dysfunction." (PMID 30659233, 2019). "Given endothelial tissues from women with preeclampsia are not readily accessible, we assessed whether we could modulate GATA2 mRNA expression in functional models of endothelial dysfunction using primary HUVECs as a model." (PMID 30659233, 2019). "Therefore, upon inflammation, endothelial SENP1-mediated SUMOylation drives GA by regulating the synergistic effect of GATA2 and NF-κB and consequent endothelial dysfunction." (PMID 28569748, 2017). "Inducing endothelial dysfunction in vitro by administering either tumour necrosis factor-α or placenta-conditioned media to endothelial cells, significantly reduced GATA2 mRNA expression (p < 0.0001), suggesting the reduced levels of circulating GATA2 mRNA may be of endothelial origin." (PMID 30659233, 2019). "Although it is widely recognised that maternal endothelial dysfunction is a major step in the development of preeclampsia, there has been no previous studies of circulating GATA2 mRNA in the disease." (PMID 30659233, 2019). "We further found that, although inducing endothelial cell dysfunction with TNFα or placental factors were associated with rising VCAM-1, when GATA2 was silenced in healthy cells, VCAM-1 was down regulated suggesting GATA2 may not be causal of endothelial dysfunction." (PMID 30659233, 2019).
Hodgkins lymphoma (3 papers, 2014 to 2025). A heterogeneous group of malignant lymphoid neoplasms of B-cell origin characterized histologically by the presence of Hodgkin and Reed-Sternberg (HRS) cells in the vast majority of cases. "The coexistence of Hodgkin lymphoma and GATA2 deficiency in this patient underscores the importance of thoroughly evaluating atypical or severe presentations of lymphoid malignancies." (PMID 41438140, 2025). "Herein, we present two Palestinian siblings with adult-onset GATA2 deficiency, one of whom developed Hodgkin lymphoma and the other cryptogenic organizing pneumonia." (PMID 41438140, 2025). "While myeloid malignancies such as MDS and AML are well-recognized complications of GATA2 deficiency, Hodgkin lymphoma has rarely been reported." (PMID 41438140, 2025). "GATA2 is mainly recognized as a modulator of early hematopoietic cell lineages and associated with progression of classical Hodgkin’s lymphoma as well as other hematopoietic diseases." (PMID 24498120, 2014). "In our first case, Hodgkin lymphoma preceded the identification of the underlying GATA2 variant." (PMID 41438140, 2025). "Our observations suggest that Hodgkin lymphoma and COP may rarely occur in the setting of GATA2 deficiency, but further studies are needed to clarify any potential associations." (PMID 41438140, 2025). "GATA2 is suppressed by SIX1 and SIX2 during erythropoiesis but activated by SIX1 in Hodgkin lymphoma." (PMID 34768865, 2021).
immunodeficiency 21 (3 papers, 2021 to 2025). "Among these, CFTR is the pathogenic gene for CF, GATA2 is associated with immunodeficiency-21, and the remaining 13 genes are associated with PCD." (PMID 40128832, 2025).